EIF4ENIF1 (eukaryotic translation initiation factor 4E nuclear import factor 1)
Description:
EIF4E-binding protein that regulates translation and stability of mRNAs in processing bodies (P-bodies). Plays a key role in P-bodies to coordinate the storage of translationally inactive mRNAs in the cytoplasm and prevent their degradation. Acts as a binding platform for multiple RNA-binding proteins: promotes deadenylation of mRNAs via its interaction with the CCR4-NOT complex, and blocks decapping via interaction with eIF4E (EIF4E and EIF4E2), thereby protecting deadenylated and repressed mRNAs from degradation. Component of a multiprotein complex that sequesters and represses translation of proneurogenic factors during neurogenesis (By similarity). Promotes miRNA-mediated translational repression. Required for the formation of P-bodies. Involved in mRNA translational repression mediated by the miRNA effector TNRC6B by protecting TNRC6B-targeted mRNAs from decapping and subsequent decay. Also acts as a nucleoplasmic shuttling protein, which mediates the nuclear import of EIF4E and DDX6 by a piggy-back mechanism.
Synonyms: 4E-T; FLJ21601; Clast4; 2610509L04Rik
Tractability: Small molecule: a structure with a bound ligand is known. PROTAC: UniProt records ubiquitination sites on it; ubiquitination databases record sites on it; its protein half-life has been measured.
Gene: Protein-coding gene on chromosome 22 (31,436,977 to 31,497,047, reverse strand). Ensembl gene ENSG00000184708.
Subcellular location: Cytoplasm, P-body; Cytoplasm; Nucleus; Nucleus, PML body; Nucleus speckle
Subcellular location (Human Protein Atlas): Vesicles; Cytosol
Gene Ontology:
Molecular function: kinase binding; nuclear export signal receptor activity; protein binding; RNA binding; mRNA binding
Biological process: miRNA-mediated gene silencing by inhibition of translation; mRNA stabilization; negative regulation of deadenylation-dependent decapping of nuclear-transcribed mRNA; negative regulation of translation; P-body assembly; positive regulation of nuclear-transcribed mRNA poly(A) tail shortening; protein import into nucleus; nuclear export
Cellular component: cytoplasm; cytosol; membrane; nuclear speck; nucleus; P-body; cytoplasmic ribonucleoprotein granule; PML body
Genetic constraint (gnomAD): Loss-of-function variants: 23 observed, 114.38 expected, observed/expected ratio (o/e) 0.2, 90% interval 0.14 to 0.28. The upper end of that interval is the gene's LOEUF score, 0.28, which puts it in group 1 of 6, group 1 being the genes least tolerant of losing a copy. Missense variants: 1,031 observed, 1,280.8 expected, observed/expected ratio (o/e) 0.8, 90% interval 0.76 to 0.85. Synonymous variants: 440 observed, 459.15 expected, observed/expected ratio (o/e) 0.96, 90% interval 0.88 to 1.04.
Homologues: Orthologues: chimpanzee EIF4ENIF1 (99% identical), macaque EIF4ENIF1 (96% identical), dog EIF4ENIF1 (96% identical), pig EIF4ENIF1 (96% identical), guinea pig EIF4ENIF1 (94% identical), rabbit EIF4ENIF1 (94% identical), rat Eif4enif1 (91% identical), mouse Eif4enif1 (90% identical), tropical clawed frog eif4enif1 (67% identical), Drosophila melanogaster 4E-T (22% identical), Drosophila melanogaster cup (18% identical).
Diseases named in the same sentence as EIF4ENIF1 in open-access papers:
EIF4ENIF1 is named in the same sentence as 5 diseases in open-access papers, as found by Europe PMC text mining. Sharing a sentence is not in itself a finding about the gene and the disease. The quoted sentences say what the papers report.
Infertility (2 papers, 2024 to 2025). "Mutations in eIF4ENIF1 cause infertility in women, in agreement with both eIF4E1b and eIF4ENIF1 working together to regulate maternal mRNA dormancy." (PMID 38177902, 2024). "We hypothesize that EIF4ENIF1 dysregulation could be an upstream cause of meiotic division errors associated with age-related infertility in women." (PMID 40441896, 2025). "Women with heterozygous mutations in EIF4ENIF1 suffer a form of early-onset infertility called POI." (PMID 40441896, 2025).
tumor (1 paper, 2023). "TalaA downregulated the phosphorylation of a series of transcription factors, including JUN, NFATC1, EIF4EBP1, ABL, RPS6KB1, and EIF4ENIF1, most of which play pivotal roles in cell proliferation and tumor progression." (PMID 37866481, 2023).
EIF4ENIF1 also shares sentences with these, for which no sentence is quoted: cancer (1 paper); menopause (1); Premature ovarian insufficiency (1).